FGF21 (fibroblast growth factor 21)
Diseases named in the same sentence as FGF21 in open-access papers (continued):
Sharing a sentence is not in itself a finding about the gene and the disease.
atherosclerosis (continued). "Studies have also documented that FGF21 inhibits endothelial cell apoptosis and promotes DNA synthesis and differentiation of endothelial cells, which has been verified in the development of atherosclerosis." (PMID 36213282, 2022). "Paradoxically, patients with atherosclerosis have high serum FGF21 levels." (PMID 36006939, 2022). "In addition, studies have reported the preventive effect of FGF21 on atherosclerosis and coronary artery disease (CAD) through protecting endothelial function and antioxidation." (PMID 36213282, 2022). "However, the exercise increases the expression of the downstream receptor of FGF21, thereby increasing the sensitivity of FGF21, which is more meaningful in preventing atherosclerosis." (PMID 36006939, 2022). "Fibroblast growth factor 21 (FGF21) is produced by cardiac cells, may acts in an autocrine manner, and was suggested to has a cardioprotective role in atherosclerosis." (PMID 36180826, 2022). "Another animal experiment showed that FGF21 reduced ROS production and alleviated atherosclerosis possibly by reducing NLRP3 inflammasome-mediated pyroptosis of vascular endothelial cell, maintaining normal mitochondrial dynamics, and inhibiting VEC endoplasmic reticulum stress." (PMID 35909513, 2022). "In preclinical studies, there was more robust reduction in TG and elevation in HDL-C with pemafibrate compared with fenofibrate, as well as enhanced cholesterol efflux from macrophages, upregulation of fibroblast growth factor 21 (FGF-21), reduced inflammation and attenuation of atherosclerosis." (PMID 33392801, 2021). "According to studies, FGF-21 has a role in the prevention of atherosclerosis." (PMID 34659937, 2021). "Fibroblast growth factor 21 (FGF21), an emerging metabolic hepatokine, has been shown to exert beneficial effects on critical atherosclerotic pathways and has been reported to be an independent predictor of subclinical atherosclerosis." (PMID 33996935, 2021). "However, one study reported that serum FGF21 concentration was significantly lower in patients with subclinical atherosclerosis." (PMID 34513950, 2021). "Thus, it is still worth for further exploration on the role of miRNA-33 in the effect of FGF21 on DM-induced atherosclerosis." (PMID 34349728, 2021). "FGF21 analogs are therefore potential therapeutic targets for atherosclerosis." (PMID 33996935, 2021). "Recently, clinical studies have indicated that FGF21 levels increase in atherosclerosis." (PMID 32227589, 2020). "We identified a potential role for FGF21 analogs in the treatment of atherosclerosis." (PMID 32227589, 2020). "Thus, FGF21 appears to exert its protection against atherosclerosis by multiple actions on the blood vessels, liver, adipose tissues, and exergy metabolism." (PMID 32957703, 2020). "Several studies have been conducted to investigate the role of FGF21 in atherosclerosis." (PMID 32957703, 2020). "In summary, these results suggest that DCA may be therapeutic for patients with atherosclerosis via increasing BAT activation through AMPK-induced FGF21." (PMID 31570705, 2019). "We found that the protective effect of FGF21 against atherosclerosis might be due to its inhibitory effects on Fas/FADD-mediated apoptosis." (PMID 30157856, 2018). "In their study, the protection against atherosclerosis by FGF21 might be in part due to its inhibitory effects on ER stress-mediated apoptosis, and this mechanism of FGF21 is different from that found in our results." (PMID 30157856, 2018). "Apoptosis is important in the process of atherosclerosis, and thus, whether FGF21 inhibits HUVEC apoptosis was explored." (PMID 30157856, 2018). "In this study, we investigated the role of FGF21 in suppressing the progression of atherosclerosis, and we tested the hypothesis that FGF21 could inhibit Fas-mediated apoptosis in apoE−/− mice." (PMID 30157856, 2018).
atherosclerosis (continued). "We speculate that FGF21 prevents atherosclerosis through a mechanism that involves reducing Fas/FADD-mediated apoptosis in endothelial cells." (PMID 30157856, 2018). "Our results show that FGF21 could protect HUVECs against ox-LDL-induced apoptosis and provide evidence that FGF21 hinders the exacerbation of atherosclerosis in apoE−/− mice, revealing that FGF21 is a metabolic disorder regulator for cardiovascular disease." (PMID 30157856, 2018). "Interestingly, FGF21 has been evidenced to prevent atherosclerosis via inhibiting SREBP-2 expression." (PMID 27905947, 2016). "Specifically, FGF21 prevented atherosclerosis and subsequent coronary heart disease was attributed to multiorgan cross talk among the liver, adipose tissue, and blood vessels and was characterized by suppression of lipid accumulation and increased lipid oxidation." (PMID 27247947, 2016). "Furthermore, serum FGF21 levels positively correlate with carotid and iliac lesions in patients with subclinical atherosclerosis, especially in women." (PMID 26594197, 2015). "The presence of elevated FGF21 levels in patients with subclinical atherosclerosis may also be attributed to a compensatory response, secondary to FGF21 resistance." (PMID 26047614, 2015). "Fibroblast growth factor 21 (FGF21) is an emerging metabolic regulator associated with glucose and lipid metabolism, and it is still unclear whether FGF21 is related to atherosclerosis." (PMID 25850006, 2015). "The role of FGF21 in atherosclerosis has been highlighted recently." (PMID 26047614, 2015). "Another study found the protective effect of FGF21 on atherosclerosis might be in part due to its inhibition on endoplasmic reticulum stress-mediated apoptosis." (PMID 25850006, 2015). "Furthermore, exogenous FGF21 infusion to the CMECs atherosclerosis promoting culture significantly inhibited the apoptosis of cells." (PMID 25850006, 2015). "As in the case of BNP, mRNA expression levels of FGF21 were demonstrated to be increased in rat cardiac micro-vascular endothelial cells cultured under atherosclerosis-like conditions, and the addition of exogenous FGF21 potently inhibited the apoptosis of cardiac endothelial cells." (PMID 26091256, 2015). "Serum FGF21 levels were detected by enzyme-linked immunosorbent assay in 212 newly diagnosed type 2 diabetic patients without clinical symptoms of atherosclerosis or cardiovascular diseases." (PMID 26047614, 2015). "The mechanism linking FGF21 with atherosclerosis was currently not well understood." (PMID 25850006, 2015). "Elevated mRNA expression of FGF21 was found in rat cardiac micro-vascular endothelial cells (CMECs) cultured in atherosclerosis-like conditions; furthermore, exogenous FGF21 infusion to the CMEC atherosclerosis-promoting culture significantly inhibited the cells’ apoptosis." (PMID 23981342, 2013). "The most dangerous atherosclerosis manifestation is coronary atherosclerotic heart disease and research efforts have focused on defining the relationship between metabolic-related and inflammation-related serum factors (such as FGF21) and CAD." (PMID 23981342, 2013). "Therefore, this rise in FGF21 level may be a compensatory response to protect the heart from atherosclerosis induced by BaP and an atherogenic diet." (PMID 39108652, 2024). "In addition, FGF21 regulates critical cellular processes in macrophages, vascular endothelial cells, and vascular smooth muscle cells, protecting against the development of atherosclerosis and CAD." (PMID 39335642, 2024).
atherosclerosis (continued). "Several studies indicated that FGF21 by its anti-oxidative and anti-inflammatory effects and its influences on lipid profile and adiponectin expression could, directly and indirectly, decrease atherosclerosis incidence." (PMID 36457562, 2022). "Therefore, reducing FGF21 resistance and improving its sensitivity may be an approach to prevent atherosclerosis." (PMID 36006939, 2022). "Growing evidence suggests that FGF21 may reduce atherosclerosis incardiovascular disease." (PMID 39077619, 2022). "Furthermore, clinical studies revealed a potential association of high circulating levels of FGF21 in serum with atherosclerosis as well as CAD, independent of established cardiovascular risk factors." (PMID 35909513, 2022). "Therefore, it is believed that FGF21 prevents atherosclerosis may be mediated by inhibiting the expression of miRNA-33 to repress SREBP2 hepatic expression." (PMID 34349728, 2021). "In addition, FGF21 can also play a therapeutic effect on atherosclerosis through the NF-κB pathway." (PMID 34675822, 2021). "The association between FGF21 with subclinical atherosclerosis in women independent of markers of inflammation may suggest other pathways, for example, involving vascular hemodynamics, as the dominant process in women." (PMID 33996935, 2021). "Moreover, FGF21 can prevent atherosclerosis by regulating the interconnection among adipose tissue, liver and blood vessels, and activating the angiotensin converting enzyme 2-angiotensin axis for preventing angiotensin II-induced hypertension and vascular damage." (PMID 34675822, 2021). "Likewise, the beneficial actions of FGF21 on atherosclerosis were identified by inducing adiponectin production from adipose tissues and decreasing the hepatic expression of the transcription factor sterol regulatory element binding proteinλ, resulting in reduced cholesterol synthesis." (PMID 31570705, 2019). "Consequently, elevated circulating FGF21 levels may represent a feedback defense mechanism of the body in response to vascular damage in rodents with atherosclerosis." (PMID 30157856, 2018). "Thus, we explored whether FGF21 was involved in the pathogenesis of atherosclerosis in apoE−/− mice." (PMID 30157856, 2018). "Therefore, our current study provides the possibility that FGF21 may be effective for the prevention and treatment of atherosclerosis." (PMID 30157856, 2018). "However, no study has examined whether the association differed by sex, which has been reported between FGF-21 and atherosclerosis." (PMID 29021814, 2017). "Indeed, high levels of FGF21 may be a compensatory reaction to offset atherosclerosis, suggesting that FGF21 might be a potential therapeutic target for this disease." (PMID 26047614, 2015). "High levels of FGF21 may be a compensatory reaction to offset atherosclerosis." (PMID 26047614, 2015). "However, the relationship between circulating FGF21 and subclinical atherosclerosis or atherosclerosis of other arteries such as the femoral and iliac artery remains unclear." (PMID 26047614, 2015). "Considering these results in conjunction with the collective findings from previous related clinical studies, serum FGF21 elevation may represent a regulatory compensation mechanism under atherosclerosis conditions, and may represent a promising therapeutic target for this disease." (PMID 23981342, 2013). "FGF21 is gaining recognition as a prospective addition to the FGF family, potentially playing a significant role in cardiovascular disease, particularly atherosclerosis." (PMID 38333506, 2024). "Background/Objectives: Fibroblast growth factor 21 (FGF21) is a hormonal regulator of lipid and glucose metabolism exerting protection against atherosclerosis by multiple actions on the blood vessels, liver, and adipose tissues." (PMID 39452947, 2024).
atherosclerosis (continued). "An extensive body of literature have demonstrated the protective effects of recombinant FGF21 or FGF21 analogues in preclinical models of NASH and atherosclerosis as well as in patients with NASH, serving as an attractive therapeutic marker for both diseases." (PMID 37200978, 2023). "Whether the high level of FGF-21 in patients with DM or atherosclerosis is supposed to provide protection against vascular injury or inflammation in atherosclerosis or is simply a new biomarker for CV diseases due to resistance to FGF-21 remains to be elucidated." (PMID 33810243, 2021). "It has been found that endogenous FGF21 expression is downregulated, but sterol regulatory element-binding protein 2 (SREBP2) expression is upregulated in a rat experimental atherosclerosis model." (PMID 34349728, 2021). "Finally, focusing on fibroblast growth factor 21 (FGF21), recent studies showed that its function is not limited to the regulation of metabolism, but that it is also involved in the protection of multiple physiological processes, such as oxidation, inflammation, atherosclerosis, and aging processes." (PMID 30150532, 2018). "In summary, we described the effect of FGF21 in suppressing apoptosis induced by ox-LDL in HUVECs and the progression of atherosclerosis." (PMID 30157856, 2018). "However, circulating FGF21 levels in type 2 diabetic patients with or without subclinical atherosclerosis or its association with atherosclerosis of other arteries such as the femoral and iliac artery remain unclear." (PMID 26047614, 2015). "While this study is the first to provide clinical evidence of the relationship between serum FGF21 level and CAD diagnosed by coronary arteriography, further animal studies should be conducted to reveal the exact mechanism between FGF21 and atherosclerosis." (PMID 23981342, 2013). "Clinical studies have revealed direct correlations between reduced serum FGF21 levels and the development of various CVDs, such as myocardial ischemia, CAD, cardiac hypertrophy, atherosclerosis, and diabetic cardiomyopathy, supporting the protective function of endogenous FGF21 against CVDs." (PMID 39335642, 2024). "In addition, a study on autophagy showed that FGF21 upregulation of RACK1 induced autophagy and inhibited atherosclerosis." (PMID 38451046, 2024). "Sappanwood extract could regulate the FGF21/SREBP-2 signaling pathway to alleviate lipid metabolism disorders and atherosclerosis in rats." (PMID 37576954, 2023). "FGF21 can also inhibit endothelial cell pyroptosis mediated by NLRP3 inflammasome and reduce aortic pyroptosis mediated by the NLRP3 inflammasome to prevent atherosclerosis." (PMID 36006939, 2022). "Endoplasmic reticulum (ER) stress is another factor that may increase FGF21 concentrations, it is well known that FHTG subjects have high postprandial lipemia that may lead to atherosclerosis and endothelial dysfunction with ER stress." (PMID 33588820, 2021). "Mice lacking FGF21 are more prone to hypercholesterolemia and atherosclerosis, suggesting the cardioprotective effect of elevated FGF21." (PMID 31498116, 2019). "Basic on those studies, FGF21 was suggested to be related to arteriosclerosis, but the effect of FGF21 is still not clear in atherosclerosis, an inflammatory disease that is related to metabolic disorders." (PMID 30157856, 2018). "In addition, serum FGF21 was reported to be elevated in newly diagnosed T2DM, and positively correlated with carotid and iliac lesions in patients with subclinical atherosclerosis, especially in women." (PMID 28821258, 2017). "In the current study we report for the first time that serum FGF21 levels are strikingly elevated in newly diagnosed type 2 diabetic patients with subclinical atherosclerosis compared to those without subclinical atherosclerosis." (PMID 26047614, 2015).
atherosclerosis (continued). "Serum FGF21 levels were significantly higher in patients with subclinical atherosclerosis compared to those without [261.3 (135.1–396.4) versus 144.9 (95.9–223.0) ng/L, P < 0.001]." (PMID 26047614, 2015). "Thus, it is possible that the elevated FGF21 observed in the LEAD subjects of our study represent a similar compensatory mechanism, by which the system is attempting to protect against atherosclerosis." (PMID 25850006, 2015). "Thus, it is possibly that the elevated FGF21 observed in the CAD subjects of our study represent a similar compensatory mechanism, by which the system is attempting to protect against atherosclerosis." (PMID 23981342, 2013). "This narrative review focuses on four types of batokines (FGF21, neuregulin 4, 12,13-diHOME, and BAT-derived microRNAs) for which evidence of modulation of cardiovascular function exists in the context of pathological states such as hypertension, atherosclerosis, and ischemia/reperfusion injury." (PMID 40149686, 2025). "However, the associations between FGF21 and metabolic diseases such as NAFLD, atherosclerosis, and hyperlipidemia have still not reached an agreement." (PMID 37641103, 2023). "However, there are limited data on whether aerobic exercise modulates FGF21 to inhibit pyroptosis mediated by NLRP3 inflammasome and then prevent atherosclerosis." (PMID 36006939, 2022). "Considering the mechanisms of atherosclerosis prevention induced by FGF21, the increased FGF21 may not be the basis for atherosclerotic pathogenesis while it may compensate for the increase during atherosclerosis and bring beneficial effects instead." (PMID 34513950, 2021). "To further study whether FGF21 inhibits atherosclerosis via ameliorating Fas-mediated apoptosis in apoE−/− mice, we measured the mRNA and protein expression of Fas and FADD in the apoE−/− mice and apoE−/− mice treated with FGF21." (PMID 30157856, 2018). "Whether the beneficial effects of FGF21 on lipid metabolism are enough to protect against atherosclerosis has not been investigated." (PMID 30157856, 2018). "Furthermore, serum FGF21 levels were strikingly higher in patients with subclinical atherosclerosis compared to patients without subclinical atherosclerosis [261.3 (135.1–396.4) versus 144.9 (95.9–223.0) ng/L, P < 0.001]." (PMID 26047614, 2015). "Despite FGF21 was closely related to T2DM and CAD, the specific mechanism by which FGF21 participated in the occurrence of CAD has not been elucidated, and study mainly referred to atherosclerosis." (PMID 35909513, 2022). "In addition, we found a positive correlation between serum FGF21 with iliac IMT but not with femoral IMT in both genders, which suggests that there may be some differences in the pathogenesis of atherosclerosis in these 2 vessels even though they are nearby." (PMID 26047614, 2015).